SPOCK1 (SPARC (osteonectin), cwcv and kazal like domains proteoglycan 1)
Diseases named in the same sentence as SPOCK1 in open-access papers (continued):
Sharing a sentence is not in itself a finding about the gene and the disease.
gastric cancer (continued). "Meanwhile, some reports revealed that SPOCK1 may promote the invasion and metastasis of gastric cancer and glioma and may confer a poor prognosis in urothelial carcinoma." (PMID 33293473, 2020). "More importantly, SPOCK1 expression was found to be related with E‐cadherin, Slug and Vimentin expressions [P < 0.001, Contingency coefficient (C) = 0.431; P = 0.015, C = 0.234; P = 0.005, C = 0.271] in gastric cancer tissues." (PMID 28940639, 2018). "Besides, the expression levels of SPOCK1, E‐cadherin, Slug and Vimentin were detected in gastric cancer tissues and in adjacent normal gastric mucosas of 102 patients with gastric cancer by immunohistochemical staining." (PMID 28940639, 2018). "The elevated SPOCK1 expression is closely correlated with cancer metastasis and patient survival, and SPOCK1 promotes the invasion and metastasis of gastric cancer through Slug‐mediated EMT, thereby possibly providing a novel therapeutic target for gastric cancer." (PMID 28940639, 2018). "In addition, knockdown of SPOCK1 expression significantly inhibits the invasion and metastasis of gastric cancer cells in vitro and in vivo, inversely, SPOCK1 overexpression results in the opposite effect." (PMID 28940639, 2018). "However, in the light of our present knowledge, the function of SPOCK1 in the gastric cancer metastasis remains uncharacterized, and even less is known about the underlying mechanism responsible for SPOCK1‐mediated cancer progression." (PMID 28940639, 2018). "Therefore, we investigated the role of SPOCK1 in gastric cancer metastasis and its potential mechanism(s)." (PMID 28940639, 2018). "Interestingly, Kim 19 first revealed that SPOCK1‐mediated EMT signalling conferred acquired resistance to lapatinib in human epidermal growth factor receptor 2 (HER2)‐positive gastric cancer." (PMID 28940639, 2018). "We demonstrated a significant positive correlation between high expression of SPOCK1 in primary lesion and poor prognosis in patients with gastric cancer, and a conclusion that SPOCK1 contributed to the invasion and metastasis of gastric cancer via Slug‐mediated EMT." (PMID 28940639, 2018). "Furthermore, positivity for SPOCK1, Slug or Vimentin expression negatively correlated with post‐operative overall survival in patients with gastric cancer (P < 0.05, respectively)." (PMID 28940639, 2018). "Previous studies have shown that SPOCK1 may facilitate cancer metastasis in gastric cancer." (PMID 36397112, 2022). "We found frequent expression of SPOCK1 (in both nuclei and cytoplasm), MCL-1 and SOX9 in gastric cancer." (PMID 35221802, 2022). "SPOCK1 and epithelial‐mesenchymal transition (EMT)‐related biomarkers were detected by immunohistochemistry and Western blot in gastric cancer specimens." (PMID 28940639, 2018). "Regarding the mechanism(s) of SPOCK1‐induced cells invasion and metastasis, we prove that Slug‐induced EMT is involved in SPOCK1‐facilitating gastric cancer cells invasion and metastasis." (PMID 28940639, 2018). "Several studies have focused on the prognostic values of CAF-related genes in other cancers, a 4-CAF-gene (COL8A1, SPOCK1, AEBP1 and TIMP2) prognostic signature was developed to predict the clinical outcomes and the response to anti-tumor therapies in gastric cancer." (PMID 35873482, 2022). "In line with our findings, a previous study showed that SPOCK1 facilitated EMT in gastric cancer through the activation of SLUG rather than SNAIL26." (PMID 32555336, 2020). "To determine the expression level of SPOCK1 in gastric cancer, we initially examined SPOCK1 protein in 40 pairs of gastric cancer tissues (tumour samples and noncancerous gastric samples) by Western blot." (PMID 28940639, 2018). "Intriguingly, SPOCK1 expression has been shown to induce EMT in multiple cancer cell lines, including gall bladder, lung, and esophagus, and has been demonstrated to confer resistance to HER2 target therapy in gastric cancer cell line through EMT." (PMID 27626636, 2016).
gastric cancer (continued). "Hence, in the next step, whether the PI3K/AKT signals involved in SPOCK1‐induced EMT in the invasion and metastasis of gastric cancer deserves further investigation." (PMID 28940639, 2018). "Among them, SPOCK1 expression was highest in SGC7901 and SNU216 cells and was lowest in AGS cells and GES‐1 cells, which indicated that SPOCK1 was overexpressed not only in primary tumours but also in gastric cancer cell lines comparing with corresponding normal controls." (PMID 28940639, 2018). "However, SPOCK1 had a negative effect on CSCs in gastric cancer." (PMID 35360859, 2022). "However, in this study of ours, to exclude the possibility that the positive role of SPOCK1 in cell migration and invasion was as a result of different proliferation rates, our data showed that SPOCK1 almost did not affect the proliferation of gastric cancer cells in vitro and in vivo assays." (PMID 28940639, 2018).
breast carcinoma (11 papers, 2012 to 2025). "Ultimately, we found that knockdown of ANXA2 in breast cancer-associated fibroblasts not only affected the expression of SPOCK1 but also led to a decrease in IGF1 expression." (PMID 40837013, 2025). "This study aimed to systematically explore the expression pattern, prognostic significance, mutation landscape, immune association, and spatial localization of SPOCK1 in breast cancer through integrated multi-omics analyses." (PMID 40837013, 2025). "This study aims to further investigate the role of SPOCK1 in breast cancer, focusing specifically on its function in cancer-associated fibroblasts." (PMID 40837013, 2025). "High SPOCK1 levels were also associated with poor clinical outcome in a subset breast cancer patients." (PMID 28103946, 2017). "Consistent with the association between SPOCK1 expression and such aggressive phenotypes, we have shown a significant correlation between SPOCK1 expression and poorer overall survival in our breast cancer cohort." (PMID 27626636, 2016). "Notably, high SPOCK1 expression was significantly associated with poor prognosis in breast cancer patients, including reduced overall survival (OS), progression-free interval (PFI), and disease-specific survival (DSS)." (PMID 40837013, 2025). "However, the underlying mechanisms by which SPOCK1 contributes to breast cancer progression and metastasis—particularly its functional role within the tumor microenvironment—remain largely unclear." (PMID 40837013, 2025). "Based on these findings, we hypothesized that ANXA2 might act as an upstream regulator of SPOCK1 in breast cancer-associated fibroblasts (CAFs)." (PMID 40837013, 2025). "Interestingly, high SPOCK1 expression levels were associated with adverse clinical outcome in the same subsets of breast cancer patients predicted by EPCR levels." (PMID 28103946, 2017). "Our finding supports the role of certain myoepithelial markers in tumor progression and suggested that the alteration of the TGF-β pathway may be a potential cause of SPOCK1 dysregulation, conferring poor prognosis in breast cancer." (PMID 27626636, 2016). "SPOCK1, a matricellular glycoprotein, has been implicated in tumor progression, metastasis, and the tumor immune microenvironment, yet its specific roles in breast cancer (BRCA) remain unclear." (PMID 40837013, 2025). "SPOCK1 serves as a critical regulator of breast cancer progression, influencing tumor metastasis and reshaping the immune microenvironment via CAF-mediated mechanisms." (PMID 40837013, 2025). "In our study, SPOCK1 expression was significantly elevated in breast cancer tissues, particularly in bone metastases, where it was predominantly expressed in cancer-associated fibroblasts (CAFs)." (PMID 40837013, 2025). "In breast cancer CAF cell lines with knockdown of ANXA2 we found that the expression of both SPOCK1 and IGF1 was reduced." (PMID 40837013, 2025). "In our study, single-cell transcriptomic analysis elucidated the cell type-specific expression pattern of SPOCK1 within the breast cancer microenvironment." (PMID 40837013, 2025). "UALCAN also showed mRNA expression of SPOCK1 in 33 kinds of cancers, in which several cancers, including breast cancer, exhibited increased SPOCK1 expression." (PMID 33293473, 2020). "It has been suggested that EPCR-mediated matricellular secretion of proteoglycan SPOCK1/testican-1 was responsible for inducing breast cancer growth." (PMID 30626007, 2019). "Cell growth kinetics was evaluated in control and EPCR and SPARC/osteonectin, Cwcv, and kazal-like domains proteoglycan (SPOCK1/testican 1) silenced breast cancer cells in 2D, 3D, and in co-culture conditions." (PMID 28103946, 2017). "Taken together, these results indicate that SPOCK1 is a relevant factor for primary tumor growth in breast cancer." (PMID 28103946, 2017). "The expression of SPOCK1 in up to 66.7% of MBC but rarely in other subtypes of breast carcinoma is remarkable." (PMID 27626636, 2016).
breast carcinoma (continued). "In conclusion, we identified SPOCK1 as a novel TGF-β–induced myoepithelial marker and further demonstrated that SPOCK1 enhanced invasion in breast cancer cells and correlated with poor prognosis in breast cancer clinical samples." (PMID 27626636, 2016). "In breast cancer, SPOCK1 exhibited a complex relationship with immune cell infiltration." (PMID 40837013, 2025). "Based on these findings, we hypothesize that in breast cancer, SPOCK1-positive CAFs may involve a synergistic interaction between ANXA2 and SPOCK1 to regulate tumor EMT and metastasis." (PMID 40837013, 2025). "Moreover, SPOCK1 is reported promoting the proliferation and migration in many other cancers like colon cancer, pancreatic cancer and breast cancer via NF-κB pathway or AKT/mTOR pathway." (PMID 35360859, 2022). "Moreover, breast cancer patients (GSE2034 cohort) with high EPCR expression also had significantly higher SPOCK1 expression levels." (PMID 28103946, 2017). "Indeed, SPOCK1 silencing in breast cancer cells impaired the number of 3D spheres and primary and metastatic tumor growth, an effect that phenocopied EPCR silencing." (PMID 28103946, 2017). "To test the hypothesis that certain MEC markers may have tumor progressive effect and confer adverse prognosis in breast cancer, we characterized the functional role of SPOCK1." (PMID 27626636, 2016). "We demonstrated a novel role of TGF-β in the induction of the MEC marker, SPOCK1, and the finding may suggest that alteration of the TGF-β pathway may be a potential cause of SPOCK1 dysregulation conferring poor prognosis in breast cancer." (PMID 27626636, 2016). "To further determine the biological significance of SPOCK1 in breast cancer, we investigated the expression of SPOCK1 in 478 invasive ductal carcinoma (IDC) cases through immunohistochemistry and correlated the expression with clinicopathological characteristics." (PMID 27626636, 2016). "Moreover, in the present study, we demonstrated that SPOCK1 enhanced invasion in breast cancer cells and correlated with poor prognosis in breast cancer clinical samples." (PMID 27626636, 2016). "Single-cell transcriptomic analysis further confirmed that SPOCK1 expression was significantly higher in CAFs from tumor tissues than from adjacent normal tissues, implying that SPOCK1 may contribute to breast cancer metastasis, especially bone metastasis, through CAF-mediated mechanisms." (PMID 40837013, 2025). "This study systematically explored the expression pattern and clinical significance of SPOCK1 (SPARC/osteonectin, CWCV and Kazal-like domains proteoglycan 1) across multiple cancer types, with a particular focus on its role in breast cancer." (PMID 40837013, 2025). "Subsequently, we compared the expression levels of SPOCK1 and IGF-1 between parental breast cancer fibroblasts and ANXA2-knockdown breast cancer fibroblasts." (PMID 40837013, 2025). "To further investigate the interaction between ANXA2 and SPOCK1, we constructed GARS-knockdown breast cancer fibroblasts using ANXA2-specific siRNA." (PMID 40837013, 2025). "We found that the expression of both SPOCK1 and IGF-1 was reduced in ANXA2-knockdown breast cancer fibroblasts." (PMID 40837013, 2025). "SPOCK1 and TGFB1I1 (also called hydrogen peroxide-inducible clone 5) are induced by TGF-β and promote breast cancer cell invasion." (PMID 33420367, 2021). "We overexpressed SPOCK1 through transient transfection in MCF10A cells and 2 breast cancer cell lines, T47D and MB231, and performed invasion assay." (PMID 27626636, 2016). "In conclusion, we identified SPOCK1 as a novel TGF-β–induced MEC marker and further demonstrated that SPOCK1 enhanced invasion in breast cancer cells and correlated with poor prognosis in breast cancer clinical samples." (PMID 27626636, 2016).
breast carcinoma (continued). "We were able to show that FXYD3 and PTX3 expression is associated with poor overall patient survival in SCC patients and LAD1, SLC7A5, SLPI, NID2, SPOCK1 and SULF1 correlated significantly with impaired pCR in breast cancer patients." (PMID 23251436, 2012). "Notably, SPOCK1 was altered by EPCR to mediate 3D growth, consequently promoting breast cancer progression." (PMID 33293473, 2020). "Taken together, these findings support the role of SPOCK1 mediating EPCR effects and suggest that EPCR could promote 3D growth of breast cancer cells by altering tumor-matrix interactions by modulating SPOCK1." (PMID 28103946, 2017). "From the upregulated genes of the EMT-core gene list, high PTX3 expression tends to poor overall survival of SCC patients (p = 0.16) and high expression of NID2 (p = 0.0091), SPOCK1 (p = 0.038) and SULF1 (p = 0.00029) significantly correlated with impaired pCR of breast cancer patients." (PMID 23251436, 2012). "Strikingly, when stratifying breast cancer by HER2 expression, we found that the communication between SPOCK1+ CAFs and epithelial cells was markedly enhanced in HER2-positive subtypes, suggesting that SPOCK1 may contribute to subtype-specific breast cancer progression." (PMID 40837013, 2025). "SPOCK1 protein expression in non-IDC breast carcinoma subtypes." (PMID 27626636, 2016).
colorectal cancer (10 papers, 2018 to 2025). A primary or metastatic malignant neoplasm that affects the colon or rectum. "It has been reported that the expression of SPOCK1 in colorectal cancer is closely associated with immune infiltration and the expression of CD206, a marker for M2 macrophages." (PMID 38087364, 2023). "SPOCK1 plays a significant role in the establishment of a phenotype of colorectal cancer cell resistant to 5-FU." (PMID 37046698, 2023). "Recent discoveries have revealed that SPOCK1 is overexpressed in colorectal cancer, non-small cell lung cancer and glioblastoma." (PMID 33293473, 2020). "A previous study revealed that deregulating the expression of SPOCK1 suppressed colorectal cancer (CRC) proliferation in vitro and vivo, and SPOCK1 was involved in CRC malignant features." (PMID 33293473, 2020). "Additionally, SPOCK1 upregulation in colorectal cancer cells enhances 5-fluorouracil resistance by regulating PRRX1 expression and downstream apoptosis signaling." (PMID 40860778, 2025). "G ROC analysis for SPOCK1 predicting aberrant methylation in colorectal cancer." (PMID 37779184, 2023). "SPOCK1 was significantly highly expressed in liver cancer, pancreatic cancer, and colon cancer cells and correlated with tumor immune infiltrates in colorectal cancer as one of the valuable prognostic biomarkers." (PMID 37779184, 2023). "Interestingly, some of the recent studies suggest knockdown of SPOCK1 inhibits the proliferation and invasion in colorectal cancer cells in vitro and in vivo." (PMID 35046388, 2022). "Therefore, our data highlight the therapeutic potential of targeting miR-135/SPOCK1 to enhance the treatment of colorectal cancer." (PMID 35046388, 2022). "Hypermethylated genes of ZNF471, SND1, SPOCK1, FBLIM1, and OTX1 were obtained from methylation chip detection and further confirm analysis in colorectal cancer and adenoma compared with normal tissue, which may be promising diagnostic markers of colorectal cancer and colorectal adenoma." (PMID 37779184, 2023). "Five hypermethylated genes including ZNF471, SND1, SPOCK1, FBLIM1, and OTX1 were detected and confirmed in 68 cases of colorectal cancer, 31 cases of adenoma, and 49 cases of normal control group." (PMID 37779184, 2023). "The methylation degree of ZNF471 was more than 2.9-fold, SND1 was more than 14.5-fold, SPOCK1 was more than 5.8-fold, FBLIM1 was more than 11.1-fold, and OTX1 was more than 6.9-fold in colorectal cancer or colorectal adenoma to that in the normal control." (PMID 37779184, 2023). "Our results indicated that ZNF471, SND1, SPOCK1, FBLIM1, and OTX1 methylation may be useful in diagnosing colorectal cancer and adenoma." (PMID 37779184, 2023). "Previous studies reported that SPOCK1 could mediate EMT by the Wnt/β-catenin signaling pathway in non-small cell lung cancer, the PI3K/AKT signaling pathway in colorectal cancer, among other pathways." (PMID 33293473, 2020). "Hypermethylated genes of ZNF471, SND1, SPOCK1, FBLIM1, and OTX1 were obtained from methylation chip detection and further confirm analysis in colorectal cancer and adenoma compared with normal tissue, which may be promising diagnostic markers of CRC and colorectal adenoma." (PMID 37779184, 2023).
gallbladder cancer (8 papers, 2015 to 2024). "As a potential cancer prognostic marker, SPOCK1 enhanced proliferation and metastasis in gallbladder cancer cells via the PI3K/AKT pathway." (PMID 39494300, 2024). "Moreover, SPOCK1 blocked gallbladder cancer (GBC) cell apoptosis and promoted cell proliferation and metastasis by activating PI3K/Akt signaling both in vitro and in vivo." (PMID 33293473, 2020). "Interestingly, it is worth to note that PI3K/AKT signalling pathway was involved in SPOCK1‐mediated EMT in gallbladder cancer 13 and glioma cancer." (PMID 28940639, 2018). "Recently, SPOCK1 has been shown to promote epithelial-mesenchymal transition (EMT) and metastasis in other tumors including lung and gallbladder cancer and hepatocarcinoma." (PMID 28103946, 2017).
colon cancer (7 papers, 2020 to 2023). "The human colon cancer tissues data downloaded from TIMER also showed that SPOCK1 and POSTN were positively correlated with CD68 and CD206 in colon cancer tissues." (PMID 36611136, 2023). "Similarly, the knockdown of the SPOCK1 gene has been shown to suppress the malignant tumor characteristics of colon cancer cells." (PMID 38087364, 2023). "Second, the expression of SPOCK1 and POSTN was only verified in several cases of colon cancer due to limited resources." (PMID 36611136, 2023). "Apart from SPARC, the other genes correlating with immune infiltration included SPOCK1 and INHBA which were highly correlated with CAFs in colon cancer, as well as TUBB (correlations with myeloid dendritic cells in thymoma)." (PMID 36604669, 2023). "Our finding that SPOCK1 is downregulated in CRC is in contrast with TCGA data and with previous research that demonstrated its overexpression in colon cancer and in other tumour types." (PMID 32599859, 2020). "In addition, our tissue specimens also showed significant overexpression of SPOCK1 and POSTN in tumor cells and CAF for colon cancer." (PMID 36611136, 2023). "Above results, it is not difficult to find that SPOCK1 and POSTN related to CAF are co-expressed with CD68 and CD206 in colon cancer, which indicates that the CAF-associated POCK1 and POSTN expressions have an important influence on macrophages, especially M2 macrophages." (PMID 36611136, 2023).